L1CAM (L1 cell adhesion molecule)
Diseases named in the same sentence as L1CAM in open-access papers (continued):
Sharing a sentence is not in itself a finding about the gene and the disease.
neuroblastoma (continued). "Here we repeated the functional evaluation of L1CAM-specific CAR T cells with different spacer lengths in 2D cocultures and directly compared functionality with that in bioprinted 3D neuroblastoma models." (PMID 34267756, 2021). "To test the functional significance of FAS induction on neuroblastoma cells for CAR T cell efficacy, we combined SP-2509 and L1CAM-specific CAR T cell treatments in vitro." (PMID 34771652, 2021). "For neuroblastoma, there are some studies looking into CAR-T cell therapy targeting for example L1CAM or GD2; however, results remain unsatisfactory." (PMID 34575700, 2021). "To test the efficacy of L1CAM-specific CAR T cells against neuroblastoma cells expressing varying antigen levels, we first quantified L1CAM expression in different neuroblastoma cell lines using flow cytometry and standardized QuantiBRITE calibration beads." (PMID 34771652, 2021). "TAAs identified in neuroblastoma include disialoganglioside GD2 and L1 cell adhesion molecule (L1-CAM)." (PMID 32899932, 2020). "Pathways involved in regulating treatment resistance and apoptosis as regulated by L1CAM include PI3K/Akt signaling in gastric cancer, retinoblastoma and neuroblastoma." (PMID 31455004, 2019). "For example, chimeric antibodies chCE7 targeting L1CAM that were developed in the 1980s bind the CE7 epitope of L1 and are internalized by neuroblastoma and renal carcinoma cells." (PMID 30116755, 2018). "L1CAM-CAR T cells were separated into 2 groups by their capability to infiltrate (or not) a 3D bioprinted neuroblastoma model." (PMID 41394860, 2025). "In neuroblastoma, lncRNA XIST was reported to enhance radioresistance through miR-375/L1CAM axis." (PMID 35600868, 2022). "We present live-cell and fluorescence microscopy methods to visualize interactions between second-generation L1CAM-specific CAR T cells with the 4-1BB costimulatory domain harboring the short or long spacer and tumor cells in these bioprinted 3D neuroblastoma models." (PMID 34267756, 2021). "We used a three-dimensional (3D) bioprinting approach for large-scale generation of highly reproducible 3D human tumor models for the test case, neuroblastoma, and compared these to 2D cocultures for evaluation of CAR T cells targeting the L1 cell adhesion molecule, L1CAM." (PMID 34267756, 2021). "Yet, with the exception of a phase-I trial with CAR-T cells in neuroblastoma patients (, see also Section 5), to date no L1CAM-based treatments have reached clinical use, although there are biotech companies that are actively pursuing this goal." (PMID 32429448, 2020). "L1CAM serves as a target for the treatment of various types of cancer using monoclonal antibodies and antibody fragments, and neuroblastoma is not an exception in this context." (PMID 30116755, 2018). "Despite the fact that L1CAM expression is a poor prognostic factor for various types of tumors, the situation is not so obvious for neuroblastoma." (PMID 30116755, 2018). "Robust L1CAM expression is not exclusive to neuroblastoma cell lines." (PMID 37943774, 2023). "Furthermore, exquisite expression of certain proteins in neuroblastoma owing to the unique developmental origin, such as GD2 or L1-CAM, may also be exploited as distinct and exclusive targets for next generation immunotherapies." (PMID 37993280, 2023). "We did not use the L1CAM-negative Raji cell line, derived from a Burkitt lymphoma, for this experiment because the primary focus for our study was to show an effect on a solid tumor such as neuroblastoma." (PMID 34771652, 2021). "We tested the in vivo capacity of L1CAM-CAR T cells with and without SELPLG to infiltrate a neuroblastoma xenograft tumor generated from the SK-N-AS cell line in an immunodeficient NOG mouse model." (PMID 41394860, 2025).
neuroblastoma (continued). "Strikingly, comparing neuroblastoma SH-SY5Y cells that have no detectable α-syn to SH-SY5Y cells that stably express α-syn (SH/+αS), we found that expressing α-syn increased L1CAM and single-cell motility by 54% and 597%, respectively." (PMID 37286800, 2023). "FAS upregulation sensitized neuroblastoma cells to death via the FAS-FASL axis and enabled L1CAM-directed CAR T cells to eradicate antigen-negative tumor cells in vitro." (PMID 34771652, 2021). "FAS upregulation sensitized neuroblastoma cells to FAS-FASL-dependent death, and enabled L1CAM-directed CAR T cells to eradicate antigen-negative tumor cells in vitro." (PMID 34771652, 2021). "Functional characterization of L1CAM-CAR T cells genetically modified to enforce these characteristics demonstrated that neither trait negatively impacted L1CAM-CAR T cell cytotoxicity, activation and cytokine release upon coculture with neuroblastoma target cells." (PMID 41394860, 2025).
pancreatic cancer (41 papers, 2010 to 2026). "In vitro investigations in pancreatic cancer cells have shown that L1CAM expression is rather associated with resistance to conventional cytotoxic agents." (PMID 27233077, 2016). "In pancreatic cancer, expression of L1CAM is associated with a chemoresistant and migratory phenotype." (PMID 25860483, 2015). "L1CAM-associated chemoresistance has also been proposed in pancreatic cancer." (PMID 32429448, 2020). "L1CAM has been implicated in tumor metastasis and therapeutic antibodies that target this molecule block tumor growth in experimental models of ovarian and pancreatic cancer." (PMID 24884715, 2014). "Lactate promotes histone H3K18 lactylation, increasing the transcription of neural invasion‐associated genes such as L1CAM and SLIT1, thereby driving PNI in pancreatic cancer." (PMID 41556039, 2026). "For example, L1 cell adhesion molecule (L1CAM), initially linked to neuronal migration, is overexpressed in pancreatic cancer PNI." (PMID 40696378, 2025). "L1CAM expression levels in pancreatic cancer tissues appear to be lower than in surrounding normal tissues." (PMID 39201435, 2024). "In the present study, we evaluated the expression of selected CSC markers (CD133, CD44, and L1CAM) with immune checkpoint inhibitor (PD-L1) in pancreatic cancers." (PMID 39148690, 2024). "Conversely, L1CAM seems to suppress stemness-related traits in pancreatic carcinoma, suggesting that the role of L1CAM in CSC depends on the tumor type and/or on the cellular context." (PMID 34645505, 2021). "To clarify L1 function in PDAC and cellular phenotypes, we performed L1CAM cell sorting, silencing and overexpression in several primary pancreatic cancer cells." (PMID 32291413, 2020). "Using a TMA and analysing the Human Protein Atlas database we found that L1CAM is downregulated in the majority of pancreas carcinomas." (PMID 32291413, 2020). "Lund and collaborators generated a pancreatic carcinoma cell line resistant to the chemotherapeutic 5-Fluorouracil (5-FU) and, upon transcriptomic profiling, identified L1CAM interaction pathway as one of the top-ranking hits among 319 upregulated genes." (PMID 32429448, 2020). "Neuropilin-1, a binding partner of L1CAM in the nervous system, was found in pancreatic carcinoma cells and proposed to interact with endothelial L1CAM, again favoring transendothelial migration." (PMID 28134764, 2017). "Thereafter, in vivo studies were conducted on an orthotopic model of pancreatic carcinoma treated with L1CAM-neutralizing antibodies." (PMID 28134764, 2017). "A recent study on antibody therapy to human L1CAM in pancreatic carcinoma cells in a transgenic mouse model showed also a significant reduction of tumor size after treatment with the mAb L1-9.3/2a." (PMID 27174921, 2016). "Our results point towards a specific role for L1CAM in the proliferation of 5-FU-resistant pancreatic cancer cells." (PMID 25860483, 2015). "Our findings provide further insight into the molecular mechanisms leading to a chemoresistant and migratory phenotype in pancreatic cancer cells and highlight the importance of addressing Slug-induced L1CAM expression in recurrent pancreatic cancer." (PMID 25860483, 2015). "Our findings provide further insight into the molecular mechanisms leading to a chemoresistant and migratory phenotype in pancreatic cancer cells and highlight the importance of addressing Slug-induced L1CAM expression in recurrent PDAC." (PMID 25860483, 2015). "Positive L1CAM expression has been reported in ~80% of analyses of pancreatic tumor samples and cell lines." (PMID 24660028, 2014). "PCR analysis showed that L1CAM mRNA was present in the seven pancreatic cancer cell lines, Capan-2, PANC-1, AsPC-1, BxPC-3, SW-1990, Patu-8988 and CFPAC-1." (PMID 24660028, 2014). "The effect of L1CAM silencing on proliferation and cell cycle distribution in Capan-2 pancreatic cancer cells was determined by CCK-8 and flow cytometric assays, respectively." (PMID 24660028, 2014).
pancreatic cancer (continued). "Although L1CAM mRNA was observed in the seven human pancreatic cancer cell lines that were investigated in the present study, the level was highest in the Capan-2 cells." (PMID 24660028, 2014). "The human Capan-2 pancreatic cancer cell line was infected with lentivirus-mediated short hairpin RNA (shRNA) to target L1CAM." (PMID 24660028, 2014). "The presence of L1CAM in tumor tissue and cultured cells has been correlated with poor prognosis and advanced-stage pancreatic cancer." (PMID 24660028, 2014). "L1CAM was overexpressed in esophageal adenocarcinoma, pancreatic cancer, colorectal cancer, gallbladder carcinoma, extrahepatic cholangiocarcinoma, gastric cancer, and cholangiocarcinoma, notably at the invasive front of the tumors." (PMID 24422715, 2013). "Given the critical role of L1CAM in pancreatic cancer PNI, we established a PANC-1 sciatic nerve injection model with circNFIB overexpression and/or lentiviral-mediated L1CAM knockdown (sh-L1CAM) to evaluate the therapeutic potential of L1CAM as a target for PNI intervention." (PMID 40963905, 2025). "L1CAM is a 200~220-kDa (L1-200-220) transmembrane glycoprotein, and its overexpression was shown to induce invasion, metastasis, stemness, and chemoresistance in several solid tumors such as ovarian, endometrial, and pancreatic cancers." (PMID 38263290, 2024). "L1CAM induces perineural invasion in pancreatic cancer cells." (PMID 37566075, 2023). "Other studies could also show that L1CAM‐overexpressing colon carcinoma cells display higher growth rates, while downregulation of L1CAM inhibits proliferation of pancreatic cancer cells." (PMID 34228897, 2022). "Besides, ezrin binding to L1CAM which is elevated in invasive colorectal tumor fronts is essential for proliferation, invasion, and metastasis of colorectal, but also breast and pancreatic cancer cells (for review, see Ref." (PMID 34228897, 2022). "The finding on tumor-suppressing role of L1CAM in reversing stemness in the EMT activation process offers prognostic value since restoration of L1CAM expression contributes to sensitizing pancreatic cancer cells to chemotherapy and in turn enhancing prognosis for patients with PDAC." (PMID 33928036, 2021). "Indeed, anti-L1CAM antibodies improved the efficacy of chemotherapeutic drugs in preclinical models of ovarian and pancreatic cancer." (PMID 32429448, 2020). "Yet whether a Slug/L1CAM axis accounts for chemoresistance in pancreatic carcinoma remains to be investigated." (PMID 32429448, 2020). "Furthermore, in pancreatic cancer, L1CAM promotes, via α5-integrin para- or autocrine signaling of IL1β, which induces iNOS activation and NOS secretion, leading to the inhibition of caspase 3 and 7 activity." (PMID 31455004, 2019). "The interaction between L1CAM-FL-ECD and integrins leads to activation of integrins and downstream phosphorylation and activation of focal adhesion kinase (FAK), proto-oncogene tyrosine-protein kinase Src, and integrin-linked kinase in pancreatic cancer." (PMID 31455004, 2019). "In addition to integrins, L1CAM also binds to L1CAM in trans and promotes the proliferation of pancreas cancer cells in vitro." (PMID 28504692, 2017). "Furthermore, pre-incubating tumor-derived ECs with anti-L1CAM antibodies prevented the adhesion and the transendothelial migration of pancreatic cancer cells." (PMID 28134764, 2017). "Further studies are planned to investigate whether treatment with anti-L1CAM antibodies will reduce growth or metastasis of our 5-FU-resistant pancreatic cancer cell lines in vivo." (PMID 25860483, 2015). "L1CAM has been linked to EMT in several different cancer types, including pancreatic cancer." (PMID 25860483, 2015). "In the present study it was hypothesized that the suppression of L1CAM expression in human pancreatic cancer cells may inhibit tumor progression." (PMID 24660028, 2014).
pancreatic cancer (continued). "Therefore, in order to assess the impact of L1CAM knockdown on the development of pancreatic cancer in vitro, Capan-2 cells were infected with lentivirus-mediated L1CAM-specific shRNA." (PMID 24660028, 2014). "The aim of the present study was to establish the effect of silencing L1 cell adhesion molecule (L1CAM) on the proliferation, invasion, cell cycle progression and apoptosis of pancreatic cancer cells, and to determine the potential molecular mechanisms that are involved." (PMID 24660028, 2014). "In addition, studies have found that L1CAM is aberrantly expressed in a variety of tumor types, including human gliomas, non-small cell lung cancer, and ovarian, colorectal and pancreatic cancer." (PMID 24660028, 2014). "In summary, the present review emphasizes the roles of some microRNAs, GATA6, L1CAM, and MUC1 in pancreatic cancer." (PMID 40699746, 2025). "Suppresses the proliferation and metastasis of pancreatic cancer cells by down-regulating the activities of STAT3, NF-κB, and L1CAM." (PMID 41211420, 2025). "This review aims to discuss the new functions of important biomarkers, such as miRNAs, GATA6, L1CAM, and MUC1 in pancreatic cancer." (PMID 40699746, 2025). "In addition, L1CAM-integrin binding was shown to induce interleukin (IL)-1β production in pancreatic cancers, and IL-1β was reported to transactivate EGFR in OSCC, implying that the interaction of L1CAM and integrin might promote EGFR activation via inducing IL-1β upregulation in OSCC." (PMID 38263290, 2024). "The L1 cell adhesion molecule (L1CAM), also known as CD171, and neural cell adhesion molecule (NCAM), also called CD56, regulate neural adhesion/migration and are expressed by Schwann cells and pancreatic cancer cells." (PMID 36497277, 2022). "The expression of L1CAM is increased by TGF-β treatment in endometrial and pancreatic cancer cells in a SLUG-dependent fashion." (PMID 33710805, 2021). "In breast and pancreatic cancer, TGF-β1 was shown to induce an EMT-like phenotype and leads to expression of L1CAM." (PMID 31952346, 2020). "Moreover, LOXL2 promotes the activation of FAK/SRC and is involved in regulation of expression of CDH1, Snail, and L1CAM, all of which are related to EMT and invasiveness of pancreatic tumor cells." (PMID 38560567, 2024). "Driven by their microarray data and by previous observation in pancreatic cancer, the authors knocked down Slug and β-catenin in chemoresistant cells and found that the former, but not the latter, modulates L1CAM protein levels." (PMID 32429448, 2020). "By combining a mouse model of L1CAM-negative pancreatic carcinoma with the endothelial-specific ablation of L1CAM, we implicated vascular L1CAM in tumor angiogenesis and, as a consequence, in tumor growth and metastasis." (PMID 28134764, 2017). "Moreover, LOXL2 contributes positively to the activation of FAK/SRC and influences the expressions of CDH1, Snail and L1CAM, which are all related to EMT and the invasiveness of pancreatic tumor cells." (PMID 27285767, 2016). "In addition, treatment of pancreatic cancer cell lines with the EMT inducer, transforming growth factor (TGF)-β1, was found to upregulate L1CAM, leading to increased cell migration and invasion." (PMID 24660028, 2014). "Downregulation of L1CAM may inhibit proliferation, invasion and arrests cell cycle progression in pancreatic cancer via p38/ERK1/2 signal pathway, and therefore, L1CAM may serve as a potential target for gene therapy in pancreatic cancer." (PMID 24660028, 2014). "Finally, a study focusing on pancreatic cancer demonstrated that, L1CAM-ECD cleaved from Schwann cells homotypically interacts with L1CAM on tumor cells leading to the activation of ERK and STAT3-mediated expression of MMP-2 and -9 which facilitates cancerous nerve invasion." (PMID 31455004, 2019).
pancreatic cancer (continued). "ERK activation, however, did not depend on L1CAM cleavage in these cells, which is consistent with findings in colorectal and pancreas cancer, that showed that expression of L1CAM-CT is, in contrast to L1CAM-FL, not sufficient to stimulate proliferation or metastasis." (PMID 31455004, 2019).